IL10 (interleukin 10)
Diseases named in the same sentence as IL10 in open-access papers (continued):
Sharing a sentence is not in itself a finding about the gene and the disease.
malaria (continued). "Cytokines such as TNF, IFN-γ and IL-10 participate in cellular and humoral immune modulation in malaria and affect pathogenesis, parasitaemia control and pathophysiology, which are dependent on the cellular and circulating levels of these cytokines." (PMID 27435973, 2016). "Multivariate regression analyses demonstrate that elevated levels of plasma sCD163 as well as IL-10 are independent parameters that significantly increase the odds of severe malaria by 4.7 fold and 1.2 fold, respectively." (PMID 27385484, 2016). "In contrast, subjects with mild malaria displayed herein higher levels of IL-10 than subjects with severe malaria." (PMID 26466783, 2015). "Further, parasitaemia levels displayed positive significant interactions with IL-6, CCL4 and IL-10 in the group of patients co-infected with malaria and dengue." (PMID 26271921, 2015). "For example, Eotaxin alone has a marginal effect when EC are compared to malaria patients, whereas it becomes significant when calculated with covariates (IL-4 and IL-10)." (PMID 26602091, 2015). "While there is a predominantly Th1 cytokine profile in CD4 T cells in healthy rural African individuals who are exposed frequently to malaria, these T cells also express high levels of IL-10 and IL-21." (PMID 26646149, 2015). "Plasma levels of pro-inflammatory (TNF-α and IFN-γ) and anti-inflammatory (IL-10) cytokines known to be involved in both pathogenesis and defence mechanisms against malaria were also measured." (PMID 26178656, 2015). "Hepcidin was positively correlated with IL-6 and IL-10 in the mild malaria group in the present study." (PMID 26466783, 2015). "The group of malaria mono-infected patients exhibited a biosignature composed by higher levels of IL-10 and CCL2 whereas the group of dengue mono-infected individuals displayed a signature with high expression of IL-4, IL-7 and Il-12 in plasma." (PMID 26271921, 2015). "IL-10 is a regulatory cytokine and the correlation between hepcidin and this cytokine can modulate the clinical disease observed in mild malaria cases." (PMID 26466783, 2015). "It is interesting to note in this context that both IL-10 blockade and blockade of PDL-1, CTLA4 and LAG3 reduced the level of circulating malaria parasites, however only IL-10 blockade restored vaccine-mediated protection." (PMID 26366739, 2015). "Hepcidin levels are increased in cases of both severe malaria and malaria with hyperbilirrubinemia, and hepcidin levels are positively correlated with IL-6 and IL-10 in the mild malaria cases, and with IFN-γ in severe malaria subjects." (PMID 26466783, 2015). "In malaria, the role of IL-10 in regulating the inflammatory response remain conflicting since several studies suggest that enhanced IL-10 is associated with increased pathogenesis while others associate with protection." (PMID 25627396, 2015). "In the placenta, levels of IL-10 were significantly increased in the women who had malaria at delivery compared to the uninfected women." (PMID 26090803, 2015). "Regarding malaria mono-infection, IL-10 and CCL2 were the immune markers with more relevant elevations in plasma." (PMID 26271921, 2015). "So far, several studies show that severe malaria is associated with increased TNF-α, IFN-γ, and IL-1β but decreased IL-10 and TGF-β." (PMID 26602091, 2015). "In order to demonstrate the role of cytokines in the modulation of HAT progression, we assayed six cytokines (IFN-γ, IL1-β, TNF-α, IL-6, TGF-β and IL-10) in plasma of both cases (N = 49, after excluding 6 malaria co-infected patients) and controls (N = 41)." (PMID 26090964, 2015). "In murine malaria models, the protective role of IL-10 in dampening excessive inflammation is well-established." (PMID 24787713, 2014). "The levels of IL-6 and IL-10 were evaluated in patients presenting the first episode of malaria, patients reporting less than five or more episodes of the disease." (PMID 24741587, 2014).
malaria (continued). "Further studies are also needed to disentangle the relative contributions of IL-10 upregulation and antibodies to protection from malaria." (PMID 24743880, 2014). "The role of anti-inflammatory cytokine IL-10 in malaria appears to enhance parasitemia since the Th1 immunological responses against the parasite are inhibited and IL-12 secretion is also suppressed by this cytokine." (PMID 24669217, 2014). "CD4+ T cell responses were measurable in nearly all children, with the majority of children having CD4+ T cells producing both IFNγ and IL-10 in response to malaria-infected red blood cells." (PMID 24415936, 2014). "In Brazilian populations, IL-10 and CRP are an important marker of acute malaria caused by P. vivax." (PMID 25309052, 2014). "Our results implicate an anti-inflammatory response induced by malaria parasites via the cytokine IL-10 in promoting increased growth of bacteria that have disseminated from the intestine to other organs of the body." (PMID 24787713, 2014). "While the levels of IL-10 and IL-6 were found independent on the number of malaria episodes, higher levels of these cytokines were seen in patients with higher parasite load." (PMID 24741587, 2014). "In an independent experiment, we sought to determine if the upregulation of P. falciparum-inducible IL-10 production after malaria influences the production of pro-inflammatory cytokines." (PMID 24743880, 2014). "The potential role that malaria-specific IFNγ/IL-10 co-producing CD4+ T cell cells play in mediating or inhibiting protective immunity in humans has not thus far been investigated." (PMID 24415936, 2014). "We confirmed that cys2 DBLα-tags induced CD4+ T cells that predominantly secrete IL-10 during the acute malaria episode." (PMID 24453249, 2014). "P. falciparum-inducible IFN-γ- and TNF-producing CD4+ T cells also increased after the resolution of malaria compared to baseline, and like IL-10, reverted to homeostasis after the dry season." (PMID 24743880, 2014). "Together these data indicate that the functional phenotype of the malaria-specific T cell response is heavily influenced by malaria exposure intensity, with IFNγ/IL10 co-producing CD4+ T cells dominating this response among highly exposed children." (PMID 24415936, 2014). "The concentration of plasma IL-10 in patients with severe anaemia has been shown to be significantly lower than in patients with uncomplicated malaria or cerebral malaria." (PMID 24520384, 2014). "One factor contributing to increased infection levels of S. Typhimurium during co-infection with malaria is induction of IL-10." (PMID 24787713, 2014). "We assessed transcription factor expression within the dominant population of malaria-specific IFNγ/IL-10 co-producing cells and found that these cells uniformly were TBet+ and FoxP3−." (PMID 24415936, 2014). "CD4+ T cell IFNγ/IL-10 responses to the polyclonal mitogen PMA/Io have previously been shown to correlate with relative protection against severe malaria." (PMID 24415936, 2014). "We quantified production of IFNγ, TNFα, and IL-10 (alone or in combination) by malaria-specific T cells, and analyzed the relationship of this response to past and future malaria incidence." (PMID 24415936, 2014). "Further studies are needed to determine if IL-10-producing Th1 cells contribute to pathogen persistence, and to the failure of humans to develop sterile protective immunity to malaria." (PMID 24415936, 2014). "The immunoregulatory cytokine IL-10 is also produced upon Plasmodium infection, and it is likely to contribute to the regulation of inflammatory responses during malaria." (PMID 24741587, 2014). "Anergic IL-10 producing T cells have also been detected in response to Plasmodium falciparum infections, which account for the largest proportion of malaria disease." (PMID 24886212, 2014).
malaria (continued). "This independent experiment confirmed that P. falciparum-inducible IL-10 is upregulated after the resolution of febrile malaria relative to baseline (P = 0.0082)." (PMID 24743880, 2014). "Together, these results suggested that malaria parasite-induced production of IL-10 by macrophages and/or neutrophils is a mechanism that compromises control of systemic bacterial infection in the co-infected mice." (PMID 24787713, 2014). "The exposure-dependent inducibility of IL-10 is also consistent with anecdotal reports of rapidly waning clinical immunity to febrile malaria in those who emigrate from malaria endemic areas." (PMID 24743880, 2014). "The use of principal component analysis and cluster analysis associated increased levels of IL-6, TNF-α, IL-10, and CRP and low levels of IL-17A predominantly with individuals with malaria alone and coinfected individuals." (PMID 25309052, 2014). "The sources of immunomodulatory IL-10 in the P. yoelii and P. chabaudi malaria models are populations of CD4 T cells." (PMID 24787713, 2014). "Thirty-four malaria candidate polymorphisms, including the sickle cell trait (HbS), were assayed on the Sequenom iPLEX platform while plasma TGF-β and IL-10 levels were measured by sandwich ELISA." (PMID 24934404, 2014). "Similar findings were obtained when analyzing the “composition” (i.e. the proportion of responding cells producing IFNγ, TNFα, and/or IL10) of the malaria-specific response and duration since last malaria infection." (PMID 24415936, 2014). "Several prior studies have reported correlations between T cell responses or IL-10 production and protection from malaria in naturally exposed children, but such studies have generally been unable to adequately account for prior malaria exposure." (PMID 24415936, 2014). "Plasma levels of IL-10 were elevated in patients with high parasitaemia and who have had more than one episode of malaria." (PMID 24359168, 2013). "Our results confirm the known protective effect of HbS against severe malaria and also reveal a protective effect of SNPs in interleukin-10 (IL10) cerebral malaria and hyperpyrexia." (PMID 24312262, 2013). "High plasmatic levels of IFN-γ and IL-10 as well as lower TNF levels were also detected in malaria patients." (PMID 24041406, 2013). "HMS patients in areas characterized by seasonal malaria develop high levels of anti-Csp antibody levels, and HMS is associated with an elevation of IFNγ and IL10 cytokines." (PMID 23533445, 2013). "Here, an intense secretion of IFN-γ and IL-10 as detected by dosage of plasmatic levels, were shown in malaria patients." (PMID 24041406, 2013). "The production of IFNγ and IL10 cytokines in response to malaria antigens has been shown to be important in induction and maintenance of immunity to malaria in naturally exposed population." (PMID 23533445, 2013). "Higher plasmatic levels of IFN-γ and IL-10 as well as lower TNF levels were observed in both malaria and individuals infected with P. vivax than control individuals." (PMID 24041406, 2013). "The second source of IL-10 in 3-cure mice was CD3(+) cells which were considered as the predominant IL-10 producers in infected naïve B6 mice in previous malaria studies." (PMID 23724100, 2013). "Previous in vitro studies have shown that IL-10 suppresses the expression of malaria parasite-induced production of TNF by PBMC." (PMID 24041406, 2013). "Significantly high levels of IL-10 in plasma was observed from malaria-infected children and this corresponded with a reciprocal decrease in IL-12p70 levels, similar to that reported in other studies." (PMID 23294670, 2013). "Studies targeting on human IL-10 producing B cells in people living in malaria-endemic regions should be conducted to clarify the whole spectrum of similar resistant mechanism in humans." (PMID 23724100, 2013). "We compared the plasma TNF-α and IL-10 concentrations in malaria-infected groups with those in the lupus group." (PMID 24319531, 2013).
malaria (continued). "Higher frequencies of IFN-γ and IL-10 producing CD3+ cells and elevated IL-10, IFN-γ, MCP-1 and IL-13 in plasma were individually associated with increased malaria incidence, at different time points." (PMID 22280502, 2012). "Nonetheless, levels of IL-10 in these malaria groups were significantly higher than those of the healthy controls (8.20 ± 5.96 pg/ml, all p < 0.001)." (PMID 22682094, 2012). "The activation and expression of NF-κB p65 in peripheral blood mononuclear cells (PBMCs) of malaria patients were investigated and correlated with the levels of IL-10 and TNF to study the nature of NF-κB p65 and its linkage to inflammatory cytokines." (PMID 22682094, 2012). "It has been reported that increasing plasma IL-10 was detected in cerebral and severe malaria patients at admission, in contrast to the patients with uncomplicated P. falciparum malaria." (PMID 22682094, 2012). "IL-10 is a negative regulator of Th1 responses and of central importance in immunity to malaria, where it ameliorates immunopathology at the expense of parasite elimination." (PMID 23110184, 2012). "In another study, elevated production of IL-10 was detected in malaria-free placentas compared to malaria-infected placentas." (PMID 26623293, 2012). "The role of IL-10 in limiting the pathological consequences of malaria-induced inflammation is well established." (PMID 23144702, 2012). "In contrast, the monocytes from malaria patients produced low levels of IL-10, even when activated with TLR agonists." (PMID 22745844, 2012). "Complicated P. falciparum malaria had strikingly higher plasma IL-10 concentrations than P. vivax (p < 0.001) and uncomplicated P. falciparum (p = 0.002) patients during the acute illness (day 0)." (PMID 22682094, 2012). "In children with severe malaria, elevated levels of IL-10 have been reported to play protective role." (PMID 23323093, 2012). "Polymorphic variability in the innate immune response gene IL-10 also showed a strong haplotype risk association (OR <0.7 for the GCT haplotype) on both asymptomatic infection and clinical (mild) malaria." (PMID 22615793, 2012). "Uninfected olive baboon placentas expressed significantly higher levels of IL-4, IL-6 and IL-10 compared to malaria infected placentas, indicating that higher levels observed in this panel of cytokines were maintained in uninfected placentas." (PMID 26623293, 2012). "This is the first report showing NF-κB expression in the PBMCs of malaria patients and its correlation with IL-10 and TNF by using sandwich ELISA." (PMID 22682094, 2012). "In this model of malaria, all the inflammatory cytokines (TNFα, IFNγ, IL-1, IL-6, IL-18, IL-10) were found to be significantly elevated in the systemic circulation." (PMID 23323093, 2012). "IL10-producing Th1 T-cells had first been described over two decades ago but to our knowledge this is the first report of these cells in malaria." (PMID 22272280, 2012). "High concentrations of IL-10 and MCP-1 in plasma were associated with higher malaria incidence in both time intervals and by all analysis methods." (PMID 22280502, 2012). "Higher IL-10 production is related to reduced tissue damage in several diseases, including experimental and human malaria." (PMID 21625634, 2011). "Different macrophage subsets in patients, including those secreting IL-10, have been shown to alter malaria pathology." (PMID 21687657, 2011). "We previously examined a large panel of inflammatory cytokines and determined that IL-6 and IL-10 levels corresponded to both severity of malaria and cerebral malaria." (PMID 21447146, 2011). "Regulatory T-cells suppress activation and recruitment of T cells via production of suppressive cytokines such as IL-10 and TGF-β1, to limit the ability of dendritic cells to activate T-cells, which cause malaria related inflammation." (PMID 21439091, 2011). "Recently, it was demonstrated that filarial infection modulates malaria-specific type-1 cytokine responses in an IL-10 dependent manner." (PMID 21625634, 2011).
malaria (continued). "Serum cytokines (IL-6 and IL-10), which have previously been shown to be elevated in children with cerebral disease compared to children with alternate severe malaria diagnoses, were examined." (PMID 21447146, 2011). "In the present study, individuals presenting asymptomatic malaria displayed a lower IFN- γ/IL-10 ratio than their symptomatic counterparts." (PMID 21625634, 2011). "Other potential biomarker candidates are interleukin-10 (IL10) and the Granulocyte colony-stimulating factor (G-CSF), cytokines which are associated with susceptibility to asymptomatic malaria during pregnancy." (PMID 21929748, 2011). "Serum IFN-γ and IL-10 levels were also analysed according to the number of previous malaria episodes." (PMID 21917128, 2011). "The mean concentration of IFN-γ was 44.50 ± 75.05 pg/ml in patients with malaria, and 1.47 ± 8.43 pg/ml in the control group, while the means for IL-10 were 283.80 ± 216.71 pg/ml and 2.07 ± 4.31 pg/ml, respectively." (PMID 21917128, 2011). "Flow cytometric analysis also showed a significant increase on CD4+CD25+FoxP3+ T cells producing IFN-γ (P<0.0001), IL-17 (P = 0.0020), TGF-β (P<0.0001) and IL-10 (P<0.0001) in malaria-infected individuals." (PMID 20224778, 2010). "The role of COX during PM was questioned by quantifying at delivery COX-1, COX-2, 15-LOX, and IL-10 expression in two groups of malaria infected and uninfected placenta." (PMID 20144201, 2010). "Th2-type cytokines, such as IL-10, regulate Th1-cytokines and prevent severe forms of malaria in some animal models." (PMID 20706538, 2010). "Thus, asymptomatic malaria carriage may be linked to circulating levels of IL-10 and G-CSF." (PMID 20706538, 2010). "Those SNP associations with severe malaria are well known and are commonly reported in the literature: CR1, IL4, TNF, G6PD, IL10." (PMID 20459687, 2010). "Exposed not sensitized children also had 2- to 3-fold lower frequency of malaria antigen-driven IFNγ and/or IL-2 production (p<0.001) and higher IL-10 release (p<0.001) at 6-month follow-ups, when compared to sensitized and not-exposed children." (PMID 19636353, 2009). "As with chronic helminth infections, exposure to maternal malaria leads to the generation of significant levels of malaria blood stage antigen-driven IL-10 in cord blood and infant lymphocytes." (PMID 19478847, 2009). "Further, these immune tolerant children showed increased malaria antigen–driven IL-10 production by cord blood lymphocytes that persisted through childhood, suggesting the presence of T regulatory cells specific for malaria blood stage antigens." (PMID 19636353, 2009). "TNF-α expression showed a trend to increase in infected placentas and the balance of the immuno-modulatory molecules IL-12 and IL-10 expression denoted an anti-inflammatory response in the course of the placenta malaria pathogenesis." (PMID 19461965, 2009). "Plasma IL-12p70, sTNF-RII, IL-10 and IL-13 levels correlated with relative exposure to malaria, and with hepatosplenomegaly." (PMID 19149774, 2009). "Exposed not sensitized children had evidence for prenatal immune experience demonstrated by increased IL-10 production and partial reversal of malaria antigen-specific hyporesponsiveness with IL-2+IL-15, indicative of immune tolerance." (PMID 19636353, 2009). "In previous studies, the IL-10 (anti-inflammatory) to TNF-α (pro-inflammatory) ratio had been shown to be lower in severe malaria anaemia than in controls." (PMID 18489763, 2008). "Recent studies have shown elevated levels of circulating IL-10 in patients with cerebral and severe malaria but less so in mild malaria." (PMID 18489763, 2008). "In summary, we have identified a population of induced Foxp3− regulatory (Tr1) T cells, characterised by production of IL-10 and down regulation of IL-7Rα, that modulates the inflammatory response to malaria." (PMID 18401464, 2008).